FXYD7 (FXYD domain containing ion transport regulator 7)
Description:
Associates with and regulates the activity of the sodium/potassium-transporting ATPase (NKA) which catalyzes the hydrolysis of ATP coupled with the exchange of Na(+) and K(+) ions across the plasma membrane. Reduces the apparent affinity for external K(+), an effect that depends on the presence of external Na(+) and voltage. Increases the apparent affinity for intracellular Na(+).
Tractability: Antibody: its Gene Ontology location is reachable by antibodies, with high confidence; UniProt places it where antibodies can reach, with medium confidence; UniProt predicts a signal peptide or a membrane-spanning region. PROTAC: ubiquitination databases record sites on it.
Gene: Protein-coding gene on chromosome 19 (35,143,148 to 35,154,302, forward strand). Ensembl gene ENSG00000221946.
Subcellular location: Cell membrane
Pathways (Reactome):
Disease: Potential therapeutics for SARS
Muscle contraction: Ion homeostasis
Transport of small molecules: Ion transport by P-type ATPases
Gene Ontology:
Molecular function: protein binding; sodium channel regulator activity; ATPase binding; ion channel regulator activity
Biological process: establishment or maintenance of transmembrane electrochemical gradient; intracellular potassium ion homeostasis; intracellular sodium ion homeostasis; positive regulation of sodium ion export across plasma membrane; potassium ion import across plasma membrane; proton transmembrane transport; sodium ion export across plasma membrane; regulation of monoatomic ion transport
Cellular component: plasma membrane; membrane
Genetic constraint (gnomAD): Loss-of-function variants: 5 observed, 8.71 expected, observed/expected ratio (o/e) 0.57, 90% interval 0.3 to 1.21. That is too few expected variants to judge how well the gene tolerates losing a copy. Missense variants: 41 observed, 54.5 expected, observed/expected ratio (o/e) 0.75, 90% interval 0.58 to 0.98. Synonymous variants: 22 observed, 21.66 expected, observed/expected ratio (o/e) 1.02, 90% interval 0.73 to 1.45.
Homologues: Orthologues: macaque FXYD7 (99% identical), dog FXYD7 (90% identical), guinea pig FXYD7 (90% identical), rat Fxyd7 (88% identical), mouse Fxyd7 (86% identical). Paralogues in human: FXYD1 (31% identical), FXYD6 (28% identical), FXYD3 (26% identical), FXYD4 (26% identical), FXYD2 (24% identical), FXYD5 (22% identical).
Diseases named in the same sentence as FXYD7 in open-access papers:
FXYD7 is named in the same sentence as 6 diseases in open-access papers, as found by Europe PMC text mining. Sharing a sentence is not in itself a finding about the gene and the disease. The quoted sentences say what the papers report.
tumor (2 papers, 2021). "Analysis of the TIMER database demonstrated that FXYD1, FXYD6 and FXYD7 had significantly negative associations with tumor purity, while these genes had markedly positive correlations with CD4+ T cells, macrophages and dendritic cells." (PMID 34270462, 2021).
cancer (1 paper, 2021). A tumor composed of atypical neoplastic, often pleomorphic cells that invade other tissues. "FXYD1, FXYD3, FXYD6 and FXYD7 were significantly downregulated in cancer samples, while FXYD4 and FXYD5 were markedly overexpressed." (PMID 34270462, 2021).
FXYD7 also shares sentences with these, for which no sentence is quoted: atherosclerosis (1 paper); diabetic kidney disease (1); diabetic retinopathy (1); infection (1).